XBP1 (X-box binding protein 1)
Diseases named in the same sentence as XBP1 in open-access papers (continued):
Sharing a sentence is not in itself a finding about the gene and the disease.
ulcerative colitis (11 papers, 2010 to 2025). An inflammatory bowel disease involving the mucosal surface of the large intestine and rectum. "Inhibition of miR-330-3p prevent DSS-induced ulcerative colitis and cell apoptosis and increased XBP1 expression, suggesting that miR-330-3p might be a diagnostic biomarker of ulcerative colitis, and that XBP1 could be a potential therapeutic target for ulcerative colitis." (PMID 32386518, 2020). "Inhibition of miR-330-3p prevent DSS-induced ulcerative colitis and cell apoptosis mediated by upregulation of XBP1 expression." (PMID 32386518, 2020). "XBP1 splicing is necessary: in a study of patients with ulcerative colitis, decreased XBP1s levels were observed." (PMID 29928282, 2018). "However, all data in the present study are preclinical results, so further clinical study are warranted to figure out the effects of miR-330-3p/XBP1 network in ulcerative colitis." (PMID 32386518, 2020). "In conclusion, miR-330-3p was upregulated by DSS in both HT-29 cells and mice and promoted ulcerative colitis and cell apoptosis by targeting of 3′-UTR of XBP1, which is a key component of ER stress." (PMID 32386518, 2020). "miR-330-3p is upregulated by DSS in both HT-29 cells and mice and promoted ulcerative colitis and cell apoptosis by targeting of 3′-UTR of XBP1, which is a key component of ER stress." (PMID 32386518, 2020). "Therefore, XBP1 could be a therapeutic target for ulcerative colitis." (PMID 32386518, 2020). "A recent study reported that the use of the XBP1 agonist HLJ2 inhibited inflammation and ameliorate the ulcerative colitis." (PMID 29928282, 2018). "Also, T lymphocytes and peripheral blood mononuclear cells responded to ERS by activating the IRE1/XBP1 signaling pathway, promoting secretions of IFN-γ, IL-17A, and IL-2 in a study about ulcerative colitis." (PMID 33933165, 2021).
Alzheimer disease (10 papers, 2012 to 2021). A progressive, neurodegenerative disease characterized by loss of function and death of nerve cells in several areas of the brain leading to loss of cognitive function such as memory and language. "Moreover, a polymorphism in the promoter of the transcription factor XBP1 was identified as a risk factor of Alzheimer’s disease." (PMID 32854418, 2020). "Moreover, it has been suggested that the polymorphism -116C/G of XBP-1 gene could increase the susceptibility to develop Alzheimer’s disease in a Chinese population." (PMID 25216759, 2014). "We recently identified the protective activity of the ER stress response factor XBP1 (X-box binding protein 1) against Amyloid-ß1-42 (Aß42) neurotoxicity in cellular and Drosophila models of Alzheimer’s disease." (PMID 22528838, 2012).
bipolar disorder (10 papers, 2007 to 2023). A disorder of the brain that causes unusual shifts in mood, energy, activity levels and the ability to carry out day-to-day tasks. "This assumption is supported by the association of AD and bipolar disorder with G allele of the XBP1 rs2269577 SNP, which causes lower XBP1-dependent transcriptional activity." (PMID 36614266, 2023). "The XBP1-116C/G polymorphism is associated with an increased risk of psychiatric illness including bipolar disorder in the Asian population." (PMID 36188456, 2022). "XBP1 is involved in the endoplasmic reticulum stress response, and genopolymorphic XBP1 has been shown to increase the risk of bipolar disorder." (PMID 32285255, 2020). "A single-nucleotide polymorphism in the 116C/G gene promotor for XBP-1 has also been identified as a potential risk for bipolar disorder which affected sensitivity to mood stabilizing treatments such as lithium; however, another study found no such link." (PMID 30214045, 2019). "The importance of IRE1α/XBP1 in neuropsychiatric disorders was revealed by the identification of a single nucleotide polymorphism (SNP) in the promoter region of the XBP1 gene (116C→G substitution) in patients afflicted by bipolar disorder." (PMID 33132844, 2020). "A study in B lymphocytes from patients with bipolar disorder reported that XBP1 and CHOP are upregulated upon treatment with ER stress inducers (thapsigargin and tunicamycin), suggesting the ER stress could occur in patients with psychiatric disorders." (PMID 36188456, 2022). "IRE1 activation under induced UPR pathway can also lead to a cross-talk in glycogen synthase kinase-3 (GSK3) and XBP-1-regulated cytokine production and thus inflammatory response; GSK3 has been associated with several mood disorders like depression and bipolar disorder." (PMID 30214045, 2019). "XBP1 is a pivotal gene in the endoplasmic reticulum (ER) stress response and therefore is of interest given elevation of stress response molecules such as cortisol in patients with bipolar disorder." (PMID 23805071, 2013). "For example, 10 genes among the 16 confirmed genes (Cacng2, Dnajc3, Dusp4, Gpc6, Mbp, Nov, Phf21b, Atxn10, Xbp1, and Zfyve28) have their human orthologs located within a 10 Mb region flanking the linkage markers for bipolar disorder, and thus merit further study." (PMID 18028544, 2007). "In addition, they found that a polymorphism substitution at position 116 (C—G) in the promoter region of XBP1 lymphoblasts derived from Japanese patients with bipolar disorder conferred a reduced ER stress response that was rescued by treatment with the mood stabilizer valproate." (PMID 23805071, 2013). "XBP1 polymorphisms are associated with psychiatric disorders including SCZ, depression, and bipolar disorder in patients with or without antipsychotic treatment." (PMID 36188456, 2022). "A polymorphism (–116C→G) in the promoter region of XBP1, affecting the putative binding site of XBP1, was found to be significantly more common in Japanese bipolar patients and overtransmitted to affected offspring in trio samples of the NIMH Bipolar Disorder Genetics Initiative." (PMID 26793110, 2015).
leukemia (10 papers, 2014 to 2025). A malignant (clonal) hematologic disorder, involving hematopoietic stem cells and characterized by the presence of primitive or atypical myeloid or lymphoid cells in the bone marrow and the blood. "Over the course of 6 months Dox treatment, several mice harboring Gata1- or Xbp1-deficient leukemia succumbed to relapse, however overall survival was significantly improved relative to controls (p = 0.016 or 0.002, Mantel-Cox test)." (PMID 34764270, 2021). "Such up-front Dox resistance of immature leukemia cells may occur in both parental AML246 and its Gata1-deficient or Xbp1-deficient derivatives, and may contribute to the low frequency relapses observed with eosinophil-incapable leukemias." (PMID 34764270, 2021). "Addition of 10 μM sorafenib to human leukemia U937, Jurkat, and K562 cells was found to result in rapid accumulation of IRE1α protein and more moderate XBP1 expression, similar to application of the well-known ER stress inducers, thapsigargin, or tunicamycin." (PMID 35743086, 2022). "Only 6 of 18 mice harboring Gata1 knockout leukemia and 1 of 12 mice with Xbp1 knockout leukemia relapsed within a 6-month period on Dox, compared with 14 of 21 control mice." (PMID 34764270, 2021). "However, less frequently mutated genes IL7R, XBP1, and TOX also demonstrated high cancer effects, suggesting pivotal roles in the development of leukemia when present." (PMID 38928295, 2024). "Hence, Gata1 and Xbp1 are dispensable in immature AML246 leukemia cells but essential for leukemia maturation into the eosinophil lineage following in vivo differentiation therapy." (PMID 34764270, 2021). "Herein, artesunate (ART) induced ER stress in leukaemia cells, resulting in eIF2α phosphorylation, activation of transcription factor 4, subsequent CHOP upregulation and XBP1 splicing." (PMID 35845184, 2021). "Paradoxically, XBP-1 appears to intervene also in chronic lymphocytic leukemia, since XBP-1 inhibition interferes with leukemia cells and lymphoma survival." (PMID 25216759, 2014).
Sepsis (10 papers, 2020 to 2025). Sepsis is defined as life-threatening organ dysfunction caused by a dysregulated host response to infection. "Sig-1R associates to and restricts IRE1 endonuclease (RNAase) activity, needed for splicing the mRNA encoding XBP1 to produce active XBP1 protein in preclinical models of sepsis and inflammation." (PMID 33364957, 2020). "We observed that compared with the control group, the mRNA levels of ATF6 and XBP1 were elevated in the sepsis group." (PMID 36088483, 2022). "For example, unrestrained Ire1 activity and Xbp1 splicing in sigma-1 receptor knockout mice leads to elevated proinflammatory cytokine production and increased rates of sepsis in response to LPS treatment." (PMID 33227003, 2020). "Similarly, sepsis Th2 cells displayed upregulation of genes involved in T cell activation (XBP1; 0.66log2FC) and differentiation compared to control samples." (PMID 41208955, 2025). "Similarly, the expression levels of XBP1 and Herpud1 demonstrated a positive correlation with each other in sepsis." (PMID 40867920, 2025). "It is also indicated in the previous research that FGL2 mediates regulatory T cells and MDSCs suppressor function through inducing ROS production and promotes the activation of the XBP1 pathway and cholesterol synthesis in sepsis, which characterized by immune paralysis." (PMID 39629005, 2024). "The present results suggested that compared with the control group, the result of real-time PCR revealed the mRNA expression level of ATF6 and XBP1 both were increased in the sepsis group (both P < 0.0001) and dramatically decreased in the treatment group (P = 0.0003, P < 0.0001, respectively)." (PMID 36088483, 2022). "However, sepsis-induced AKI (LPS-related) has been driven by markedly different molecular pathologic characteristics from IR-induced AKI25, and the association between XBP1 and significant IR-induced AKI still remains to be elucidated." (PMID 33654072, 2021). "Conversely the upregulated genes in sepsis Th1 cells showed enhanced endopeptidase activity (GAPDH; 0.75log2FC) and angiogenesis related (XBP1, CXCR4, and BTG1; 0.93, 0.66, and 0.64log2FC, respectively) pathways." (PMID 41208955, 2025). "During sepsis, Sigmar1 has been shown to interact with IRE1, reducing the splicing of XBP1, resulting in reduced production of inflammatory cytokines and increasing the longevity of mice in sub-lethal models of sepsis." (PMID 34305655, 2021). "In the present septic foal study, expression levels of both XBP1 and Herpud1 decreased and exhibited a negative correlation with the sepsis score while showing a positive correlation with one another." (PMID 40867920, 2025). "Additionally, the downregulation of genes with protective function against OS, such as XBP1, HERPUD1, and SELENOS, in septic foals also highlights their significance in mitigating OS in sepsis treatment." (PMID 40867920, 2025). "In the present study, several genes associated with ER stress, including XBP1, HERPUD1, LRRK2, and SELENOS, were downregulated in foals suffering from sepsis, showing a negative correlation with the sepsis score." (PMID 40867920, 2025). "Moreover, the downregulation of genes with a protective role against OS, such as XBP1, HERPUD1, and SELENOS in septic foals, underscores their importance in alleviating OS in addressing sepsis." (PMID 40867920, 2025). "Of note, the expression levels of ATF6, XBP1 and CHOP increased in the ileal of the sepsis group." (PMID 36088483, 2022). "XBP1 and HERPUD1 (p = 0.012) exhibited a negative correlation with sepsis score while demonstrating a significant positive correlation with one another." (PMID 40867920, 2025). "In contrast, XBP1 (p = 0.002), HERPUD1 (p = 0.002), LRRK2 (p = 0.015), and SELENOS (p = 0.008) showed a significant negative correlation with sepsis score." (PMID 40867920, 2025).
Sepsis (continued). "Conversely, XBP1, HERPUD1, LRRK2, and SELENOS exhibited a negative correlation with sepsis scores and a positive correlation with the combined activities of antioxidant enzymes, highlighting the potential of ER stress as a novel therapeutic target and prognostic marker in septic foals." (PMID 40867920, 2025).
breast tumors (9 papers, 2008 to 2025). "Among the key hub nodes there was also XBP-1, one kind of basic region leucine zipper protein, which has reported having a high expression level Estrogen receptor alpha (ERα)-positive breast tumors." (PMID 32883354, 2020). "Inhibition of XBP1 through transfection with shRNA in CD44highCD24low breast tumor cells prevented paclitaxel and doxorubicin-mediated mammosphere formation." (PMID 26157705, 2015). "TCGA had previously predicted XBP1 to be an important part of a regulatory signalling hub in endometrial cancer and subsequently demonstrated that XBP1 was enriched in endometrial tumours versus breast tumours." (PMID 32069845, 2020). "The XBP1 protein is expressed in almost 80 % of ER+ breast tumours." (PMID 26459317, 2015). "The results showed that both XBP1 and XBP1s exhibited high expression levels in HR+/HER2− breast tumors." (PMID 40940685, 2025). "Then, in contrast to normal breast tissue, breast tumor tissue had considerably lower MAOB expression levels and higher levels of CYCS, XBP1, HSPA4, APEX1, and SERP1." (PMID 41367017, 2025). "The top eight genes that negatively correlated to POLR3G expression (MLPH, FOXA1, SPDEF, AR, SIDT1, AGRP2, XBP1, GATA3) are typically overexpressed in ER+ breast tumors as compared to ER- breast tumors." (PMID 36497214, 2022). "Furthermore, X-box binding protein 1 (XBP-1), a transcription factor that regulates unfolded protein/ER stress response, is frequently overexpressed in many breast tumors, but hardly detectable in non-cancerous breast tissues." (PMID 18205950, 2008).
Glucose intolerance (9 papers, 2013 to 2024). Glucose intolerance (GI) can be defined as dysglycemia that comprises both prediabetes and diabetes. "The β cell-specific deletion of XBP1 in mice resulted in a modest hyperglycaemia and glucose intolerance caused by decreased insulin secretion." (PMID 24812634, 2014). "Heterozygous Xbp1 mice exhibited significant increase in body mass associated with a progressive hyperinsulinemia and glucose intolerance when fed with a high fat diet." (PMID 24812634, 2014). "In the setting of CES2 overexpression, as in conditional XBP1 knockout mice fed a fructose diet, improving lipid homeostasis reverses glucose intolerance despite elevated ER stress." (PMID 28099843, 2017). "For example, mice with β-cell-specific deletion of Xbp-1 displayed hyperglycemia and glucose intolerance resulting from decreased insulin secretion." (PMID 26613076, 2015).
lymphoma (9 papers, 2014 to 2024). A malignant (clonal) proliferation of B- lymphocytes or T- lymphocytes which involves the lymph nodes, bone marrow and/or extranodal sites. "In the case of EBV-associated lymphomas, our results suggest that for BL, which mainly express type I latency, the targeting of IRE1α/XBP1 may be more promising than for post-transplant EBV-positive lymphomas, mainly characterized by type III latency." (PMID 36012375, 2022). "RAS-driven lymphoma cell lines actually downregulated XBP1, ATF6α, and HSP-α5." (PMID 34399819, 2021). "The close relationship between IRE1alpha/XBP1 axis activation and pro-inflammatory/immune suppressive cytokine secretion has been recently shown by our laboratory in macrophages infected by KSHV, the same virus carried by PEL cells and involved in the etiology of this lymphoma." (PMID 33513694, 2021).
osteosarcoma (9 papers, 2015 to 2025). A usually aggressive malignant bone-forming mesenchymal neoplasm, predominantly affecting adolescents and young adults. "Previously, XBP1 expression has been linked to poor outcomes in BCa, B-cell lymphomas, and osteosarcomas." (PMID 40179083, 2025). "Recent studies have shown that XBP1 increases the susceptibility of HOS osteosarcoma cells to pyropheophorbide- α methyl ester-mediated photodynamic remedies." (PMID 36303551, 2022). "Relationship between XBP1 mRNA expression and their clinicopathologic parameters in 20 of osteosarcoma." (PMID 26633383, 2015). "In osteosarcoma, the knockdown of XBP1 leads to tumor growth inhibition." (PMID 36551309, 2022). "However, there are still some limitations in the present study, in vivo studies are needed to clarify osteosarcoma cell apoptosis and proliferation caused by CENPF resulting from XBP1 and ATF6 signaling pathway." (PMID 32973403, 2020). "However, little is known about the role of XBP1 in the progression of osteosarcoma (OS)." (PMID 26633383, 2015). "In osteosarcoma, upregulation of ATF6 and E2F7 during sustained ERS suppressed E2F1 expression, upregulation of E2F7 was dependent on activation of XBP1, and downregulation of E2F1 enhanced Noxa and Puma expression and promoted ER stress-induced apoptosis." (PMID 36551309, 2022). "Finally, a recent analysis of global transcriptome (RNA-Seq) showed that CRISPR/Cas9 knockout ERK5 human osteosarcoma U2OS cells express elevated levels of CHOP, TRIB3 an XBP-1 mRNAs, compared to wild type U2OS cells." (PMID 34805151, 2021).
acute lymphoblastic leukemia (8 papers, 2014 to 2025). Leukemia with an acute onset, characterized by the presence of lymphoblasts in the bone marrow and the peripheral blood. "XBP1 upregulation predicted a poor response to therapy and shorter survival of patients with aggressive diffuse large B-cell and plasmablastic lymphomas, acute lymphoblastic leukemia (ALL), aggressive luminal B and ER+ breast cancers, and prostate cancer." (PMID 40650182, 2025). "In addition, XBP1 is crucial for the maintenance of viability of acute lymphoblastic leukemia (ALL)." (PMID 35790913, 2022). "XBP1 and also IRE1 are required during the pre-B cell stage during which immunoglobulin heavy chains are expressed for the first time, and XBP1 provides a survival benefit for tumor cells in pre-B acute lymphoblastic leukemia." (PMID 31867005, 2019).
amyotrophic lateral sclerosis (8 papers, 2010 to 2025). Amyotrophic lateral sclerosis (ALS) is a neurodegenerative disease characterized by progressive muscular paralysis reflecting degeneration of motor neurons in the primary motor cortex, corticospinal tracts, brainstem and spinal cord. "Despite the expectation that targeting XBP1 would accelerate disease progression, conditional genetic deletion of XBP1 in the CNS protects against experimental amyotrophic lateral sclerosis (ALS)." (PMID 34229656, 2021). "In a murine model of amyotrophic lateral sclerosis based on expression of G93A mutant SOD, removing Xbp1 protected from neurotoxicity, presumably through activation of a neuroprotective autophagic response." (PMID 20927324, 2010). "A very recent study identified a novel non-canonical function of the IRE1α–Xbp1 branch in regulating the proteostasis of poly (GR) via preventing its accumulation in Amyotrophic Lateral Sclerosis (ALS)." (PMID 41473415, 2025). "Amyotrophic lateral sclerosis (ALS) patients show increased PERK, ATF6, and IRE1 signaling, with higher levels of CHOP and BiP in the spinal cord, and increases in downstream elements of the UPR such as ATF4, XBP-1, and GRP58." (PMID 34360909, 2021).